CXCR3 (C-X-C motif chemokine receptor 3)
Diseases named in the same sentence as CXCR3 in open-access papers (continued):
Sharing a sentence is not in itself a finding about the gene and the disease.
melanoma (continued). "One study on breast carcinomas, melanoma, and colon cancer tissues, where the majority of TINK cells belonged to the CD56brightCD16dim subset, demonstrated high expression of dNK cell markers CD9 and CXCR3 in the breast and colon tumors." (PMID 34209508, 2021). "Expression of CCR5 and CXCR3 (receptors for CCL3-5 and CXCL9-11, respectively) on CD8+ T cells has emerged as another important regulator of effector T cell recruitment and prognosis in melanoma." (PMID 30899263, 2019). "Despite this potential induction of CXCR3 expression, CXCR3+ T cells are unlikely to reach melanoma lesions in this context." (PMID 30420855, 2018). "Collectively, these data demonstrate that host expression of CXCR3 is necessary, but not sufficient, to mediate the establishment of melanoma metastases in the lung." (PMID 28358049, 2017). "In the present study, we used an established murine model of metastatic-like melanoma to demonstrate a defect in engraftment of lungs in the absence of CXCR3+ macrophages." (PMID 28358049, 2017). "In contrast, our study directly links CXCR3 signaling with IL-8 expression in BRAFWT melanoma cells, and suggests a role for CXCR3 in melanoma progression in human cells that do not harbor the BRAFV600E mutation." (PMID 25798946, 2015). "Increased expression of surface CXCR3 protein has been correlated with hypoxia and nutrient deprivation in vitro in human breast and colon cancer cell lines, suggesting that cells expressing CXCR3 can survive and grow in the less favorable microenvironments of advanced cancer (i.e., VGP melanoma)." (PMID 25798946, 2015). "To further understand the consequences of CXCR3 expression in human melanoma cells and its role in the progression of BRAFWT melanomas in situ, we orthotopically injected 5 x 105 BOWES CXCR3 and BOWES PCMV6 cells intradermally in NSG mice (n = 16 mice per cell line)." (PMID 25798946, 2015). "Th1 (CD4+ CXCR3+) and Th1-free T helper cells (CD4+ CXCR3-) were further enriched from healthy donors and were activated with PHA or anti-CD3 antibody in the absence or presence of melanoma-derived PAEP." (PMID 25785839, 2015). "In this study we have analyzed, using flow cytometry, the systems formed by the chemokine receptors CXCR3, CXCR4, CXCR7, CCR7 and CCR10 and their ligands in thirteen human melanoma cell lines (five established from primary tumors and eight established from metastasis from different tissues)." (PMID 24559071, 2014). "CXCR3 expression in cutaneous malignant melanoma correlates with tumor progression, and is constitutively expressed in several human melanoma cell lines and mouse B16F10 melanoma cell line." (PMID 24259307, 2013). "In that study, CXCR3 was also responsible for lymph nodes metastasis of murine melanoma without affecting that of the lung indicating the role played by CXCR3 in the organ-specific metastasis of distinct cancer cells." (PMID 19436305, 2009). "Given the important role of CXCL10 in regulating CXCR3+ T cell trafficking into tumors, we next tested whether demethylation-mediated rescue of STING signaling in STINGlow B16-F10 melanoma models could restore melanoma-intrinsic CXCL10 induction." (PMID 36949064, 2023). "Nevertheless, anti-PD-1 therapy could not reduce the tumor growth in breast cancer and melanoma mouse models with CXCR3 knock-out treatment." (PMID 36845675, 2023). "Effector T cells expressed the cognate receptors CCR5 and CXCR3, thus the augmented chemokines release promoted robust infiltration of anti-tumor T cells within melanoma TME, which correlated with a better disease control and survival also in melanoma patients." (PMID 34712615, 2021). "Moreover, anti-PD-1 treatment in CXCR3 knockout mice with melanoma failed to reduce tumor growth, and this correlated with the reduced migration of T cells into tumors." (PMID 34944392, 2021).
melanoma (continued). "As melanoma cells may express CXCR3, it was also investigated whether or not short-term exposure of melphalan induced CXCR3 expression on melanoma cells." (PMID 32002296, 2020). "However, when comparing the expression of CXCR3 on melphalan-exposed and non-exposed melanoma cells in vitro, it was apparent that melphalan induced expression of CXCR3 on melanoma cells in addition to triggering its expression on lymphocytes." (PMID 32002296, 2020). "Furthermore, B16 melanoma tumors grow more rapidly in mice lacking CXCR3, and their tumors have lower levels of T cells as compared to wild-type mice." (PMID 30873179, 2019). "Importantly, reconstitution of macrophage-depleted CXCR3−/− hosts with WT, but not CXCR3−/−, monocytes allowed intravenously-injected melanomas to engraft lungs." (PMID 28358049, 2017). "Our results demonstrate that, in BRAFWT melanomas, CXCR3 signaling mediates significant increases in IL-8 expression, suggesting that CXCR3 expression and signaling may represent a transformative event that drives the progression of BRAFWT melanomas." (PMID 25798946, 2015). "Furthermore, studies targeting CXCR3 in murine models of breast and melanoma observed inhibitory effects were specifically against tumor metastasis while the primary tumor mass was unaffected, indicating that CXCR3 has a role in promoting metastasis but not incidence." (PMID 34123844, 2021). "Regarding chemokine receptors, FGFR Mut melanoma expressed higher levels of CCR5, CCR7, CXCR3, CXCR4 and CXCR6 than their wild-type counterparts, but no statistical difference was observed (all P > 0.05)." (PMID 36426352, 2022). "Notably, CXCR3 signaling appears to be non-redundant and critical for CD8+ T cell trafficking across the endothelium of blood vessels supplying both B16 melanomas and melanoma xenografts." (PMID 30899263, 2019). "Interestingly, engagement of VLA-4 was not shown to play a role in migration (data not shown); however, CXCR3 may induce increased expression of VLA-4 and promote interaction between tumor cells and melanoma cells." (PMID 28358049, 2017).
breast carcinoma (94 papers, 2009 to 2026). "For instance, CXCR3-expressing breast cancer cells induced CXCL9/10 in lung metastasis-associated fibroblasts." (PMID 41129238, 2026). "For example, high CXCR3 expression is associated with poor prognosis in breast cancer patients, and its expression level correlates positively with tumor size and the number of metastatic lymph nodes." (PMID 40786052, 2025). "High levels of Ccl17, Cxcl13, and Cxcr3 in mammary tumors or tumor-associated macrophages induce cancer cell migration which is associated with metastasis disease." (PMID 35768767, 2022). "The breast cancer (BRCA) TCGA cohort analyzed showed high CXCR3 expression associating with better survival (hazard ratio = 1.4, p-value = 0.04)." (PMID 34440489, 2021). "In the breast cancer cohort, CXCR3 was significantly upregulated in the tumor, and associated with better survival." (PMID 34440489, 2021). "TCGA data were used to estimate abundance of immune cells in breast cancer, which demonstrated the association of CXCR3 with immune infiltration, particularly in the triple-negative subtype." (PMID 34440489, 2021). "In our studies, we found STAT‐5 and the resultant increased CXCR3 promoted the homing of PTPN2‐deficient CAR T cells to CXCL9/10‐expressing mammary tumours within 3 days of adoptive transfer." (PMID 31803974, 2020). "In mice, CXCR3 deficiency was reported to promote the development of breast cancer by stimulating the M2 polarization of macrophages." (PMID 31715586, 2019). "CXCR3 has been associated with invasion of several different types of cancer, including breast cancer and is expressed in all human breast cancer cell lines." (PMID 25629162, 2015). "IP-10 was found in 45% of human breast cancers and was associated with CXCR3 expression and lymphocytic infiltration." (PMID 25415223, 2014). "For example, elevated expression of CXCL10 and its receptor CXCR3 has been associated with breast cancer metastasis." (PMID 23056468, 2012). "Furthermore, CXCR3 expression in breast cancer is also linked to the tumor’s immune microenvironment." (PMID 40786052, 2025). "In breast cancer, the expression of CXCR3 is closely linked to tumor metastasis and prognosis." (PMID 40786052, 2025). "CXCR3 has been associated with poor survival outcomes in breast cancer patients." (PMID 40786052, 2025). "In CXCR3-deficient mouse models, breast cancer progression is accelerated, which is associated with increased M2 polarization of macrophages, suggesting that CXCR3 may play a suppressive role in regulating the tumor immune microenvironment." (PMID 40786052, 2025). "Given this perplexing pattern, in which CXCR3 was significantly upregulated in the breast cancer tumors, but also associated with better survival, we hypothesized that CXCR3 expression was associated with an antitumoral immune response." (PMID 34440489, 2021). "Importantly the CXCL10/CXCR3 axis is activated in BRCA-mutant breast cancer and has been implicated in breast cancer progression and metastasis in both in vivo and clinical studies." (PMID 31320901, 2019). "Similarly, mice deficient in the chemokine GPCR CXCR3 exhibit polarization of TAMs into M2 phenotype in breast cancer." (PMID 25110692, 2014). "In the breast cancer cell lines MCF-7 and MDA-MB-231, the expression of CXCR3 splice variants A and B, as well as CTSB, is commonly observed." (PMID 40786052, 2025). "CXCL10 and its receptor CXCR3 play a crucial role in breast cancer bone metastasis and osteoclast activation." (PMID 40786052, 2025). "Blocking the CXCL9/10-CXCR3 axis through CXCR3 inhibition has previously been proposed as a strategy for suppressing tumor metastasis to the lungs in breast cancer." (PMID 40447617, 2025). "This pilot study supports the notion that inhibition of the CXCR3 axis has an inhibitory effect on breast cancer cell growth." (PMID 40362215, 2025).
breast carcinoma (continued). "A recent study has reported that senescent epithelial cells induced by therapy can secrete SASP factors, which facilitate the invasion of breast cancer cells via the CXCL11/CXCR3/Ak strain transforming (AKT)/extracellular signal-regulated kinase (ERK) pathway." (PMID 40584290, 2025). "For example, increased expression of CXCL9 by tumor-associated DCs has been shown to enhance their interaction with CXCR3-expressing CD8+ T cells in a murine model of breast cancer." (PMID 39596815, 2024). "In summary, the CXCL10/CXCR3/Akt pathway plays an important role in relieving breast cancer pain both in the early stage by inhibiting nerve metastasis and in the late stage of metastasis." (PMID 39429695, 2024). "CXCL9, also referred to as monokine induced by IFN-γ (MIG) and induced by IFN-γ, appeared to be the highest overexpressed molecule among the CXCL9, -10, −11/CXCR3 axis found in the primary breast cancer samples that developed brain metastasis." (PMID 39262976, 2024). "In human breast cancer patients, higher numbers of CD8+ T cells or CXCR3+ T cells also associated with improved overall survival." (PMID 37055433, 2023). "MKL1 expression was positively correlated with C-C motif chemokine receptor 10 and C-X-C motif chemokine receptor 3 in breast cancer." (PMID 34761735, 2022). "SRC-3 inhibition by SI-2 or SRC-3 KD activates the Cxcl9/Cxcr3 axis in breast tumors and enhances the antitumor immune microenvironment to suppress breast cancer progression." (PMID 36316775, 2022). "In an analysis of tumor-infiltrating NK cell subsets in patients with breast cancer, CXCR3+ NK cells accounted for 60% of total NK cells." (PMID 35768424, 2022). "Further analysis of CXCR3 expression in the breast cancer cohort demonstrated its role in mediating infiltration of immune cells (particularly T cells) to the tumor." (PMID 34440489, 2021). "The findings reveal that IP-10 is capable of triggering the emergence of dormant breast cancer cells within the liver metastatic niche and identifies the IP-10/CXCR3 as a candidate targetable pathway for rational approaches aimed at maintaining dormancy." (PMID 34123844, 2021). "RNA-seq data from The Cancer Genome Atlas (TCGA) were used to correlate CXCR3 expression with breast cancer progression." (PMID 34440489, 2021). "Studies have shown that high CXCR3 expression in tumor tissues suggests poor prognosis in breast cancer, colorectal cancer, kidney cancer, and ovarian cancer, and inhibition of CXCR3 expression can reduce the production of ovarian cancer ascites." (PMID 33829065, 2021). "Subsequently, the educated CAFs then secrete CXCL9/CXCL10 to stimulate CXCR3 on breast cancer cells, thereby maintaining the cancer stemness of breast cancer cells to promote lung metastatic colonization." (PMID 33407730, 2021). "Following this trend, triple-negative breast cancer samples showed both high levels of immune infiltration and CXCR3 expression compared to the other breast cancer molecular subtypes." (PMID 34440489, 2021). "The higher expression levels of CXCR3 and IFN-γ-inducible chemokines on cancer tissues have been reported to be associated with poor survival in breast cancer, colon cancer, glioma, and lung cancer." (PMID 34501934, 2021). "CXCR3+ breast cancer cells express high levels of IL-1α/β via JNK signaling, suggesting that they can both induce CXCL9/10 in MAFs and benefit from these chemokines." (PMID 32198421, 2020). "Together, this suggests that T cells are markedly suppressed in basal-like breast cancer, and complements our results showing that systemic CXCR3 inhibition represses lung metastasis in mice." (PMID 32198421, 2020). "Previous research has shown that overexpression of CXCR3 in cancer cells (e.g., breast cancer, gastric cancer cells) can promote cancer proliferation, migration, metastasis, and angiogenesis leading to poor clinical prognosis." (PMID 33324682, 2020).
breast carcinoma (continued). "Here, the authors show that CXCR3-expressing breast cancer cells secrete IL-1 to induce a paracrine crosstalk with fibroblasts in the lung, which involves CXCL9/10 production and results in colonization of the lung." (PMID 32198421, 2020). "Once secreted from fibroblasts, CXCL9 and CXCL10 bind to CXCR3 on the surface of a subpopulation of breast cancer cells to complete a paracrine loop that promotes initiation and growth of metastasis in the lungs." (PMID 32198421, 2020). "CXCR3+ breast cancer cells secrete IL-1α/β to stimulate a crosstalk with lung fibroblasts from which they benefit through their CXCR3 receptor." (PMID 32198421, 2020). "To further characterize the CXCR3+ subpopulation of breast cancer cells, we established transcriptomic profiles of FACS-sorted CXCR3+ and CXCR3– SUM-LM1 breast cancer cells." (PMID 32198421, 2020). "Higher CXCR3 expression was found to predict favorable outcomes in breast cancer patients treated with tamoxifen." (PMID 31715586, 2019). "Secretome study in breast cancer cell lines revealed that CXCR3 was highly upregulated in aggressive cancer cells and revealed a functional role of CXCR3 as a potential target for cancer therapy." (PMID 31781593, 2019). "Regarding matrix metalloproteinases, a recent study showed that inhibition of MMP-9 by a monoclonal antibody in an immuno-competent model of HER2-positive breast cancer increased tumor-suppressive T cell infiltration and CXCR3 chemokine expression." (PMID 31482487, 2019). "In breast cancer, Ras-induced CXCL10 overexpression contributes to the development of breast tumours, and overexpression of CXCR3 is associated with poorer overall survival." (PMID 31308057, 2019). "CXC motif chemokine ligand 10 (CXCL10) and its receptor CXC motif chemokine receptor 3 (CXCR3), play important roles in the motility of breast cancer cells." (PMID 30177620, 2018). "Our results show that ACE prevents TNFα-induced migration of MDA-MB-231 metastatic breast cancer cells and inhibits TNFα-induced CXCR3 and CXCL10 expression through inhibition of the IκB kinase (IKK)-mediated NF-κB pathway." (PMID 30177620, 2018). "A. canaliculatum ethanolic extract (ACE) inhibits TNFα-induced migration of MDA-MB-231 metastatic breast cancer cells and prevents TNFα-induced CXCR3 and CXCL10 expression through inhibition of the IκB kinase (IKK)-mediated NF-κB pathway." (PMID 30177620, 2018). "CXCR3 was reported as a molecular target in breast cancer metastasis; it inhibits tumor cell migration and promotes of host anti-tumour immunity." (PMID 28841719, 2017). "In tumor cells, expression of CXCR3, and more specifically of CXCR3-A, has been correlated with poor prognosis in patients with breast cancer, colon cancer, glioma and osteosarcoma." (PMID 28878333, 2017). "Increase in CXCR3 expression has been found in many human tumors and has been correlated with poor prognosis in patients with breast cancer, colon cancer, glioma and osteosarcoma." (PMID 29146996, 2017). "Reduced tumor burden in lungs was demonstrated in CXCR3−/− mice using a long-term orthotopic (4T1 breast cancer) model." (PMID 28358049, 2017). "Our finding is in agreement with CXCR3 metastasis-promoting function in breast cancer, colon cancer, and osteosarcoma, as well as lung cancer." (PMID 26485767, 2015). "To understand the function of CXCR3 in breast cancer metastasis, we knocked down (KD) CXCR3 in 4T1 cells using shRNA." (PMID 26485767, 2015). "CXCR3 has been reported to have a metastasis-promoting function in breast cancer, colon cancer, and osteosarcoma, as well as lung cancer." (PMID 26485767, 2015). "To investigate the role of CXCR3 in breast cancer metastasis, we used the 4T1 mammary tumor model, which shares many characteristics with human breast cancer, particularly its ability to spontaneously metastasize to the lungs." (PMID 26485767, 2015).